VCAM1 (vascular cell adhesion molecule 1)
Diseases named in the same sentence as VCAM1 in open-access papers (continued):
Sharing a sentence is not in itself a finding about the gene and the disease.
retinopathy of prematurity (1 paper, 2015). A bilateral retinopathy characterized by neovascularization, scarring, retinal detachment, and eventually blindness. "Indeed, the expression of leukocyte adhesion molecules such as ICAM-1 and VCAM-1 are increased in models of OIR, and chemoattractants such as RANTES are elevated in the vitreous fluid of children with retinopathy of prematurity." (PMID 26219952, 2015).
rosacea (1 paper, 2023). A chronic erythematous skin disorder that affects the face. "It has also been reported an increased expression of the vascular cell adhesion molecule-1 (VCAM-1), the intracellular adhesion molecule-1 (ICAM-1) and E-Selectin in conjunction with high expression of LL-37, in facial skin biopsies of rosacea patients." (PMID 38260914, 2023).
rotator cuff tears (1 paper, 2021). "Fibroblasts isolated from rotator cuff tears demonstrate increased expression of the activation markers PDPN, VCAM1 and CD248.." (PMID 35096791, 2021).
salivary gland inflammation (1 paper, 2025). "With the activation of VCAM1 and ICAM1, cultured SGF expressed two adhesion molecules that characterize activated immunofibroblasts which were described in mouse models of salivary gland inflammation and in inflamed human salivary gland tissues of patients with SjD." (PMID 40277884, 2025).
sarcopenia (1 paper, 2024). Progressive decline in muscle mass due to aging which results in decreased functional capacity of muscles. "After full adjustment, ICAM‐1 and VCAM‐1 were associated with sarcopenia, low SMI and HGS." (PMID 38644163, 2024). "Among the endothelial biomarkers measured, ICAM‐1 (OR: 2.47/1‐SD increase; 95% CI: 1.62–3.75) and VCAM‐1 (OR: 1.91/1‐SD increase; 95% CI: 1.27–2.87) were independent predictors of sarcopenia." (PMID 38644163, 2024). "This indicates that ICAM‐1 and VCAM‐1 are independent endothelial biomarkers of sarcopenia in CKD." (PMID 38644163, 2024).
schistosomiasis (1 paper, 2023). An infectious disease caused by parasitic trematodes of the genus Schistosoma that colonize human blood vessels and release eggs that can cause granulomatous reactions leading to acute (swimmer's itch or acute schistosomiasis syndrome) or chronic disease. "Of note, VCAM-1 has been identified as a significant contributor to the pathogenesis of schistosomiasis, and endothelial cell treatment with an anti-VCAM-1 monoclonal antibody reduces the egg adhesion to these cells." (PMID 38239348, 2023). "Moreover, in the context of schistosomiasis, the anti-VCAM-1 blockage also reduced basal monocyte adhesion (p < 0.01)." (PMID 38239348, 2023). "Current data using mesenteric endothelial cells primed by schistosomiasis unveiled positive cooperation between P2Y2R and P2X7R signaling, increasing IL-1β release, VCAM-1 expression, and monocyte adhesion." (PMID 38239348, 2023). "However, in the infected group, the coactivation with UTP at 100 μM and ATP at 500 μM selectively upregulated VCAM-1 expression compared to P2Y2 activation alone (p < 0.001), suggesting a positive cooperation between both receptors during schistosomiasis." (PMID 38239348, 2023). "In good accordance, previous data showed that PDTC inhibits VCAM-1, but not ICAM-1, expression and highlighted the role of VCAM-1 in schistosomiasis pathogenesis." (PMID 38239348, 2023).
schwannoma (1 paper, 2024). A benign, usually encapsulated slow growing tumor composed of Schwann cells. "Schwannomas Group: ICAM-1 was the most expressed, with E-Selectin, MMP-9, PAI-1, and VCAM-1 showing moderate expression." (PMID 38306519, 2024).
sclerosing cholangitis (1 paper, 2023). A chronic, autoimmune inflammatory liver disorder characterized by narrowing and scarring of the lumen of the bile ducts. "Together these data indicate that despite a trend for increased ductular proliferation, treatment with the GLP-2 analogue teduglutide reduced secretion of proinflammatory markers, such as osteopontin and Vcam-1, from cholangiocytes in the Mdr2-/- mouse model of sclerosing cholangitis." (PMID 37572734, 2023).
secondary progressive MS (1 paper, 2025). "This inhibition reduced the expression of VCAM-1 and phosphorylated NF-κB (p-NFκB), thereby preventing BBB disruption in both relapsing-remitting MS (RRMS) and secondary progressive MS (SPMS)." (PMID 40725164, 2025).
sinus (1 paper, 2012). "ApoE−/− mice treated with ARE had significantly smaller aortic sinus lesions, lower numbers of macrophages in the aortic wall, and decreased expression levels of adhesion molecules (VCAM-1 and ICAM-1) in the vessel wall compared with control mice." (PMID 22536886, 2012).
spondyloarthritis (1 paper, 2026). "VCAM-1 may represent a more sensitive marker of endothelial activation than ICAM-1 in treated spondyloarthritis." (PMID 41928308, 2026).
sympathetic ophthalmia (1 paper, 2022). Sympathetic ophthalmia (SO) is a bilateral granulomatous anterior uveitis usually occurring within the three months following trauma or a surgical procedure involving one eye. "For example, in patients with sympathetic ophthalmia, the expression of VLA-4, VLA-5, VCAM-1, ICAM-1, and CD44 in the peripheral blood was significantly increased in acute inflammation compared to either the disease resolution phase or normal eyes." (PMID 35008929, 2022).
synovitis (1 paper, 2022). Inflammation of a synovial membrane. "Then they discovered that the expression of intercellular adhesion molecule 1 (ICAM-1) and vascular cell adhesion molecule 1 (VCAM-1), two factors in synovitis, were downregulated after the clodronate liposomes treatment, further confirming the anti-inflammation effect via macrophage depletion." (PMID 36032667, 2022).
systemic vasculitis (1 paper, 2014). "In chronic adjuvant arthritis inflammation which was associated with a systemic vasculitis, α4 integrin was important in neutrophil recruitment, but VCAM-1 was not involved." (PMID 25299673, 2014).
tuberculous pleuritis (1 paper, 1996). "We analysed levels of soluble vascular cell adhesion molecule-1 (s.VCAM-1), soluble intercellular adhesion molecule-1 (s.ICAM-1), and soluble E-selectin (sE-selectin) in serum and pleural fluid from patients with tuberculous pleuritis, by sandwich ELISA." (PMID 18475740, 1996).
unstable angina pectoris (1 paper, 2022). "This work is aimed at exploring the mechanism of inflammatory factors and soluble vascular cell adhesion molecule-1 (sVCAM-1) regulated by nuclear transcription factor-κB (NF-κB) in unstable angina pectoris (UAP)." (PMID 35942210, 2022).
urolithiasis (1 paper, 2022). Stone(s) within the urinary tract. "Our previous studies showed that the serum levels of VCAM-1 and ICAM-1 were elevated in patients with urolithiasis." (PMID 35328466, 2022).
urothelial carcinoma of the bladder (1 paper, 2022). "Angiogenesis-related marker vascular cell adhesion molecule-1 (VCAM-1) has been shown to be elevated in urothelial carcinoma of the bladder (UCB), but its predictive/prognostic role has not been determined." (PMID 35347517, 2022).
urticaria (1 paper, 2024). A vascular reaction of the skin characterized by erythema and wheal formation due to localized increase of vascular permeability. "There is limited recent primary research investigating the role of VCAM-1 and ICAM-1 in urticaria, both in vivo and in vitro." (PMID 38671667, 2024). "The primary objective of this study was to determine whether the two biological indices, VCAM-1 and ICAM-1, sampled from groups of children with urticaria, returned to normal levels after treatment." (PMID 38671667, 2024). "We focused on VCAM-1 and ICAM-1, but parallel investigation of other possible biomarkers, which were not considered in this study, and their interplay in the pathophysiology of urticaria could contribute to a more comprehensive understanding." (PMID 38671667, 2024).
vascular tumor (1 paper, 2020). "VCAM-1 may be targeted in drug delivery through the use of anti-VCAM-1 mAbs, which have been shown to enhance vascular tumor accumulation." (PMID 33202648, 2020).
venous ulceration (1 paper, 2023). "In clinical trials, diosmin decreased the expression of monocytes or neutrophils, and the endothelial activation markers of the intercellular adhesion molecule 1 (ICAM-1) and the vascular cell adhesion molecule 1 (VCAM-1) on human leukocytes in patients with venous ulceration." (PMID 37371797, 2023).
visceral leishmaniasis (1 paper, 2008). A severe form of leishmaniasis characterized by irregular bouts of fever, substantial weight loss, swelling of the spleen and liver, and anemia (which may be serious). "We report an important role for VCAM-1/VLA-4 interactions in the generation of immune responses during experimental visceral leishmaniasis caused by Leishmania donovani." (PMID 18802456, 2008).
Zinc deficiency (1 paper, 2025). A deficiency of the essential metal Zinc; an essential cofactor for many enzymes. "Zinc deficiency exacerbates these processes by upregulating molecules like vascular cell adhesion molecule-1 (VCAM-1) and intercellular adhesion molecule-1 (ICAM-1), facilitating monocyte attachment and intensifying vascular inflammation and AS progression." (PMID 40390089, 2025).
tumor (766 papers, 1998 to 2026). "Endothelial VCAM-1 expression on tumour-associated vasculature also plays a significant role in neovascularisation." (PMID 40095109, 2025). "The positive correlation between SOX18 and MEF2C in LUAD, and the strong endothelial co-expression of SOX18 with VCAM1, suggests a coordinated transcriptional module possibly orchestrating endothelial activation in tumor-associated vasculature." (PMID 41373817, 2025). "Second, clinical studies are vital to assess the associations between VCAM-1 expression and various clinical characteristics, including tumor staging and prognostic significance, of patients with GC." (PMID 40927361, 2025). "More specifically, Th1 T-cell infiltration was restricted when VCAM-1 at their surface was abrogated, leading to a loss of immune mediated tumor control." (PMID 40071851, 2025). "In the tumor tissue of nasopharyngeal carcinomas, VCAM-1 was associated with chemotherapy resistance, shorter progression free (PFS) and overall survival (OS)." (PMID 40071851, 2025). "To understand further how these CD3+ T cells are trafficked into the stroma, we also studied tumour associated BVs with the expression of the key molecules VCAM-1 and ICAM-1 that are involved in immune cell trafficking." (PMID 39792888, 2025). "VCAM1 displays a particularly strong signal along the tumor border, suggesting active crosstalk between tumor cells and the surrounding stroma or endothelium—a known function of VCAM1 in promoting tumor-associated inflammation and cell adhesion." (PMID 41373817, 2025). "Sustained activation of Notch1 signaling in tumor-associated ECs induces VCAM1 expression, neutrophil recruitment and a senescent, pro-inflammatory endothelium which promotes tumor cell adhesion, intravasation and metastasis." (PMID 38426109, 2024). "VCAM-1 promotes tumor invasion and metastasis through interaction with tumor-associated macrophages." (PMID 39767739, 2024). "An increased level of VEGF inhibits the expression of intercellular adhesion molecule-1 (ICAM-1) and vascular cell adhesion molecule-1 (VCAM-1), thereby inhibiting the adhesion of tumor-associated endothelial cells to leukocytes." (PMID 39408814, 2024). "While tumor-associated macrophages, cDC2s and monocytes all express ICAM-1, only tumor-associated macrophages express high levels of VCAM-1." (PMID 37805579, 2023). "An increasing amount of data shows that VCAM-1 is closely associated with tumour angiogenesis and metastasis." (PMID 36979820, 2023). "We also tested the impact of Vcam1 loss on tumor growth in a tail vein injection (TVI) transplantation model." (PMID 36828890, 2023). "Hif1a transcript levels were significantly higher in T-ALL cells in both organs, implicating hypoxia as a potential mechanism underlying elevated ICAM-1 and VCAM-1 levels in tumor-associated myeloid cells." (PMID 37805579, 2023). "Tumor-associated CD163+ macrophages expressing VCAM1 interacted with tumor-associated erythroid cells expressing ITGA4." (PMID 37894821, 2023). "Upregulation of both Ki67 and SOX2 within the same marginal areas of the tumors is indicative of a highly proliferative and invasive tumor cell phenotype and suggests that VCAM-1 upregulation is closely associated with the invasive front of the tumor." (PMID 35312755, 2022). "RT can also alter the tumor microenvironment and tumor-associated macrophages, induce vascular endothelial cells to express adhesion molecules (e.g., VCAM-1, E-selectin, and ICAM-1), and increase vascular permeability and chemokine expression." (PMID 36140312, 2022). "In conclusion, our study on the interaction between TAPLT and endothelium identified a novel mechanism of TAPLT-mediated, VCAM-1-dependent endothelial protection against tumor-associated damages." (PMID 35408794, 2022). "Another issue was demonstrating that the anti-adhesive effect of BZM is due to the loss of E-selectin, particularly since the BZM-sensitive tumor cells not only depend on E-selectin but also on VCAM-1 for adhesion." (PMID 35031433, 2022).
tumor (continued). "Previous studies indicated that this association was through the tumor cell surface expression of VCAM1 and alphaV integrin on the MAMs, whose activity was stimulated by CCR1 signaling." (PMID 36077870, 2022). "Various studies indicate a strong association of the VCAM-1 gene with the tumor development process, where it plays a key role in angiogenesis and supports metastasis." (PMID 35742950, 2022). "In light of angiogenesis, MDSC-released VEGF was sufficient to prohibit the expression levels of various key adhesion molecules including ICAM-1 and VCAM-1 in tumor-associated ECs, thereby preventing the adhesion and extravasation of T cells." (PMID 36439137, 2022). "In cancer, vascular cell adhesion molecule-1 (VCAM-1) has been associated with tumor angiogenesis and metastasis." (PMID 34575943, 2021). "ECs activation is characterized by increased expression of surface adhesion molecules such as VCAM1 and ICAM1 and there is evidence that VCAM-1 is closely associated with tumor neoangiogenesis and progression." (PMID 33853689, 2021). "VCAM-1 is also upregulated in tumor-associated LECs and, importantly, increases lymphatic permeability by weakening lymphatic junctions through a mechanism triggered by its interaction with integrin α4β1." (PMID 34241649, 2021). "Imaging tumor angiogenesis has been explored through targeting vascular cell adhesion molecule-1 (VCAM-1), a marker associated with metastasis and immune evasion, and anti-VCAM-1 nanobody-microbubbles have been used for ultrasound imaging of murine carcinomas." (PMID 32793488, 2020). "The chi-square test analysis demonstrated that up-regulation of VCAM1 expression was significantly associated with more aggressive tumor phenotypes, such as poor differentiation (P < 0.0001) and more distant metastases (P = 0.0271)." (PMID 32793471, 2020). "We decided to focus on E-selectin and VCAM-1 adhesion proteins because they play a key role in vascular transmigration, and both proteins have also been implicated in tumor cell recruitment during inflammation." (PMID 32934781, 2020). "Low expression of E‐selectin, intercellular adhesion molecule (ICAM) 1/2 and vascular adhesion molecule 1 (VCAM1) in tumour‐associated ECs results in the loss of tight connections in the tumour vascular endothelium." (PMID 32588948, 2020). "In tumor cells, α4ß1 and α4ß7 integrins serve as alternative ligands for VCAM-1 and have been associated with the metastatic capacity of cancer." (PMID 30657059, 2019). "DNAse 1 treatment or VCAM1-deficient tumor cells prevented such interaction and impaired metastasis." (PMID 31616408, 2019). "Up-regulation of VCAM-1 on malignant cells is associated with increased ability to metastasize and recruit tumor-associated monocytes and macrophages." (PMID 31231358, 2019). "For example, the high expression of VEGF and other growth factors reduces endothelial ICAM-1 and VCAM-1 expressions in tumor tissues, causing the lymphocyte–endothelial interactions to become inefficient." (PMID 31600937, 2019). "Recently, increasing amounts of evidence have shown that VCAM-1 is closely associated with tumor angiogenesis and metastasis." (PMID 29614819, 2018). "VCAM-1 expression is also associated with oncogenesis, tumor angiogenesis, and metastasis in gastric carcinoma." (PMID 28272300, 2017). "A recent study showed that the binding of tumor-associated macrophages to cancer cells through vascular cell adhesion molecule 1 (VCAM1) activates AKT signaling and protects cancer cells from apoptosis in the lung microenvironment." (PMID 28418888, 2017). "Vascular cell adhesion molecule-1 (VCAM-1) is closely associated with tumor progression and metastasis." (PMID 28272300, 2017). "Once tumor cell attach on endothelia, they cause the induction of vascular cell adhesion molecule-1 (VCAM-1) and vascular adhesion protein-1 (VAP-1), which is dependent on tumor cell-clot formation, induced by tissue coagulation factors." (PMID 27018053, 2016).